IL21 (interleukin 21)
Diseases named in the same sentence as IL21 in open-access papers (continued):
Sharing a sentence is not in itself a finding about the gene and the disease.
tumor (continued). "Early preclinical studies leveraged the overexpression of IL-21 directly in transplanted tumors or systemic administration of IL-21 plasmid DNA by hydrodynamic-mediated methods, and both of these delivery methods significantly reduced tumor growth in an NK cell- and T-cell-dependent manner." (PMID 37483629, 2023). "Moreover, a recent preclinical study suggests that IL-21 can potentiate the ability of granulocyte-macrophage colony-stimulating factor (GM-CSF) to stimulate anti-tumor immunity in mice to resist bladder cancer." (PMID 36936961, 2023). "Nevertheless, the specific mechanisms and anti-tumor effects of NK-exos stimulated with IL-15 and other cytokines such as IL-21 (NK-exosIL−15/21) in solid tumors, including HCC, remain unclear." (PMID 37484408, 2023). "Systemic delivery of IL21 inhibits tumor growth by increasing antitumor immune responses." (PMID 37546701, 2023). "Indeed, it has been reported that in the tumor microenvironment, IL-21 exerts a lot of biological activities, stimulating the Janus family tyrosine kinases (JAK), JAK1 and JAK3, as well as triggering STAT1, STAT3, and STAT5." (PMID 37759505, 2023). "We further investigated whether IL-21 is a key regulator of CRA-induced humoral immunity against the CRC tumor in vivo, by evaluating tumor growth inhibition by CRA following IL-21 neutralization." (PMID 37081540, 2023). "It is precisely because this form of medicine can more effectively direct IL-21 to tumor-specific T cells and promote the formation and proliferation of memory stem cell-like T cells with CD44low-CD62Lhigh phenotype that the therapeutic effect is greatly improved and the side effects reduced." (PMID 36936961, 2023). "Similarly, IL-15 and IL-21 were designed to be fused with the anti-PD-1 antibody to yield fusion proteins αPD-1-IL-15R and PD-1Ab21, respectively, for tumor rejection." (PMID 38049832, 2023). "Therefore, CRA promotes B cell differentiation through the IL-21/IL-21R pathway and increases the affinity of anti-tumor antibodies." (PMID 37081540, 2023). "In addition, we found that anti-PD-1 mAb treatment in both human patients and the mouse tumor model induced IL21 expression as well as greater accessibility of the Il21 gene locus." (PMID 37546701, 2023). "In HL, cytokines such as IL-21, TNF, and IL-1 may be implicated in the inflammatory responses of the tumor microenvironment." (PMID 37958472, 2023). "Furthermore, the ratio of IgG1 and IgG3 positive cells was positively correlated with the number of IL-21 positive cells within tumor lesions." (PMID 35831283, 2022). "Additionally, the combination therapy of IL-15 and IL-21 was used in rhabdomyosarcoma to enhance anti-tumor response." (PMID 36246629, 2022). "CAR-T cells with the combined expression of IL-15 and IL-21 showed a less differentiated profile and longer survival in repeated exposures to tumor cells, in addition to maintaining the expression of T-cell factor-1 (TCF-1), an important factor for the development and survival of T cells." (PMID 36172343, 2022). "Indeed, several studies reported that the addition of IL-21 or IL-15 results in increased proportion of CAR-TSCM and TCM (including WT1- and CD19-CAR-T cells) associated with enhanced persistence and anti-tumor effects." (PMID 36248810, 2022). "They showed that CAR-T cells that coexpress IL-15 and/or IL-21 were effective against tumor cells." (PMID 36172343, 2022). "IL-10+ IgA-producing B cells could be categorized as a part of Breg cells, which suppress the anti-tumor immunity, other Breg cells such as TGF-β-producing B cells or IL-21-producing B cells also limit anti-tumor immunity." (PMID 36033455, 2022). "The combined therapy of half-life-extended IL-21 and PD-1 blockade additively inhibited tumor growth in mouse models, and enhanced the activity of Th1 T cells, as well as the fraction of DC and M1 macrophages in the TME, sustaining the antitumor immune response." (PMID 35884974, 2022).
tumor (continued). "IL-21 has both tumor-promoting and tumor-suppressive effects." (PMID 36275766, 2022). "Interestingly, a recent study in a mouse model has shown that tumor-specific Tfh-B cells interactions as well as IL-21 production result in antitumor immunity by enhancing granzyme B expression by tumor-infiltrating CD8+ T cells." (PMID 35008422, 2022). "However, in the presence of IL-21, Vγ9Vδ2 T cells can develop into immunosuppressive Tregs, emphasising that both the expansion conditions and the tumour microenvironment can influence the outcome of adoptive Vγ9Vδ2 T cell transfer." (PMID 34994391, 2022). "One way to improve the in vivo persistence of CAR-NK cells in the suppressive tumor microenvironment could be by inducing the expression of stimulatory cytokines, such as IL-2, IL-7, IL-15, and IL-21." (PMID 35203609, 2022). "Taken together, these data suggested that therapeutic designs leveraging the B cell-Tfh-IL21 axis may be one of the strategies to boost anti-tumor immune response and further research is needed to translate these findings into the clinic." (PMID 35831283, 2022). "A central finding in our study is that B cell subclasses IgG1 and IgG3 play a critical role in anti-tumor response to neoadjuvant chemoimmunotherapy, and IL-21 (mainly secreted by Tfh cells) is the driving force to induce B cell isotype switching to IgG1 and IgG3, not IgA in tumor lesion." (PMID 35831283, 2022). "The present study demonstrated that the tumor microenvironment inflammatory factor IL-21 may promote PD-L1-induced, Treg-mediated tumor immune escape in a PD-1-dependent manner." (PMID 34026621, 2021). "Tfh cells recruited CD8+ T cells and B cells by secreting C-X-C motif chemokine ligand 13 (CXCL13), and promoted the maturation of B cells into antibody-producing plasma cells by secreting interleukin 21 (IL-21), thereby promoting the formation of an immunoactive tumor microenvironment." (PMID 34359579, 2021). "In addition, a pre-clinical study comparing CAR T cells secreting different γ-chain-cytokines (IL-2, IL-7, IL-15, and IL-21) found increased anti-tumor activity with all the cytokines tested, but effects were mediated through different mechanisms." (PMID 33746981, 2021). "Taken together, these results indicated that the peptide carrier CBP-12 could stimulate the secretion of IL-21 from cDC1s, thus enhancing the antigen cross-presentation and tumor-killing effects of CD8+ T cells." (PMID 34158852, 2021). "However, these TFH cells secrete significantly less IL-21 than other circulating CD4+ T cells and associate with decreased serum IL-21 levels, suggesting a severe limitation of the expected anti-tumour functions of TFH cells in DLBCL (right)." (PMID 34572910, 2021). "As PD-L1/PD-1 signaling has recently been shown to modulate the Treg homeostasis and facilitate tumor immune tolerance, we hypothesized that PD-L1/PD-1 signaling may be involved in the process of Treg generation regulated by IL-21." (PMID 34026621, 2021). "ICI treatment may restore both humoral immune responses and cytotoxic T cell activity against tumor neoantigens mediated by Tfh by elevating interleukin-21 (IL-21) secretion to B cells and CD8+ T cells, respectively." (PMID 35069566, 2021). "Although the precise mechanisms by which they mediate this anti-tumor effect are not well understood, IL-21, commonly produced by both of these helper T cell subsets, may play an important role in their anti-tumor function." (PMID 33809259, 2021). "Interestingly, the combination of IL-21 with cetuximab was also able to enhance the ability of NK cells to recognize and eliminate cetuximab-coated tumor cells." (PMID 34557197, 2021). "Moreover, functional tumor-infiltrating Tfh cells (CD4+ IL-21+) correlated positively with the infiltration of CD138+ plasma cells." (PMID 34359579, 2021).
tumor (continued). "Combination therapy of IL-21 with PD-1 or CTLA-4 previously showed efficacy in mouse tumour models, and an engineered IL-21 fused to a PD-1 antibody showed promising results by providing superior anti-tumour immunity than anti-PD-1 alone in preclinical studies." (PMID 34572910, 2021). "The fusion of IL-21 to anti-PD-1 antibody demonstrated potent anti-tumour effects in established tumour-bearing mice, accompanied with an increased frequency of Tscm-cells and expansion of tumour-specific CD8+ Tem-cells which was superior to a combination of PD-1 blockade and IL-21 infusion." (PMID 34960140, 2021). "T-cell stimulatory common γ chain cytokines IL-7, IL-15, or IL-21 are capable of supporting the generation of memory cells with improved mitochondrial fitness and less overt T-cell differentiation compared to the use of IL-2, improving anti-tumour immunity." (PMID 34960140, 2021). "To test whether the HNSCC tumor environment is capable of potentiating Treg generation through IL-21 and PD-L1, we cocultured CD4+ T cells with tumor explants from HNSCC patients with or without IL-21 and/or an anti-PD-1 neutralizing antibody." (PMID 34026621, 2021). "Moreover, other investigators have shown that mechanistic models of interleukin-21 (IL-21) therapy schedules based on tumor mass and antigenic properties can predict growth patterns of multiple tumor types in patients receiving personalized doses of IL-21." (PMID 34749885, 2021). "In addition, a new study found that by fusion of IL-21 to anti-PD-1 antibody, IL-21 can target tumor-reactive T cells to promote TSCM production." (PMID 34604060, 2021). "Additionally, we simulated the anti-tumor effects of IL-21 secreted by Tfh cells to promote B cell maturation and antibody production in the other two experimental groups of mice." (PMID 34359579, 2021). "However, the precise molecular mechanisms by which IL-21-producing CD4+ T cells coordinate this anti-tumor effect are not well understood." (PMID 33809259, 2021). "Thus, IL-21 can be fused to the anti-PD-1 antibody and is an effective strategy for increasing the anti-tumor activity of tumor-specific T cells." (PMID 35145911, 2021). "Neutralizing IL-21 could enhance the blockade effect of an anti-PD-1 antibody on Treg generation induced by IL-21high/PD-L1high clinical tumor explants." (PMID 34026621, 2021). "Relationships between tumor stromal IL-21+ cells and clinical variables." (PMID 34026621, 2021). "Due to this difference, IL-21 has its own unique roles in anti-tumor immunity." (PMID 34179083, 2021). "Therefore, targeting IL-21 to tumor-specific T cells in vivo is potentially invaluable to improving the therapeutic effects of IL-21." (PMID 33574265, 2021). "Indeed, administration of IL21 has shown strong antitumor efficacy in multiple preclinical mouse tumor models." (PMID 34869384, 2021). "All in all, the existing data shows that IL21 strongly promotes the anti-tumor immune response." (PMID 34869384, 2021). "We hypothesize that the fusion of IL-21 to anti-PD-1 antibody will concentrate IL-21 to PD-1+ T cells in vivo, which can greatly increase the effect of IL-21 on tumor-specific T cells while reducing its side effects." (PMID 33574265, 2021). "However, the frequency of IL-21+CD4+ T cells was significantly increased in the tumor tissues compared with the paired adjacent non-tumor tissues (8.03 ± 4.37% vs. 2.4 ± 1.4%, respectively, P < 0.01)." (PMID 34026621, 2021). "The increase of IL-21 mRNA in tumor tissue at the G1 stage may indicate that there are still efficient mechanisms aimed at limiting its growth, which is also reflected in the IL21/IL22 mRNA ratio value." (PMID 34300224, 2021). "Moreover, local presence of IL-21 within tumor microenvironment is likely to interact with a variety of cell types or environmental factors than its systemic occurrence, for PD-1 ligation was observed to skew TCR repertories." (PMID 34026621, 2021).
tumor (continued). "Besides, a recent study on pancreatic cancer found that IL-21 also has an anti-tumor effect by enhancing NK cell function." (PMID 34386015, 2021). "Finally, we found that approximately half of the IL-21+CD4+ T cells in the tumor tissues were IFN-γ positive (45.6 ± 5.2%) and that IL-21+CD4+ T cells were rarely IL-4 (0.8 ± 0.3%) or IL-17 (1.6 ± 0.5%) positive." (PMID 34026621, 2021). "The anti-tumor functions of Th9 cells is mediated by IFN-γ and IL-21 while IL-9 could also directly kill tumor cells, thus we tested whether PP2A mediated inhibition of Th9 cells abrogates its anti-tumor functions via suppressing IFN-γ production." (PMID 32620893, 2020). "Furthermore, TIM-3 and PD-1 blockade combined with IL-21 revived the anti-tumor effects of exhausted NK cells in patients with advanced MHC class I-deficient tumors." (PMID 32714324, 2020). "A large amount of clinical data indicates that IL-21, as a component of the tumour microenvironment, is commonly present in the serum of DLBCL patients and may be involved in the pathogenesis and disease progression of DLBCL19–22." (PMID 32704112, 2020). "However, IL-21 contributes to tumor rejection in an NKG2D-dependent manner in multiple mouse tumor models." (PMID 33584718, 2020). "Additionally IL-21 augments the survival of CD8+ T cells resulting in a less activated but more persistent T cell phenotype that leads to enhanced tumor and viral control." (PMID 32457754, 2020). "Indeed, CD8+ T cells incubated with IL-21 showed enhanced tumor regression in an adoptive cell transfer mouse study." (PMID 32471032, 2020). "However, the authors reported that the anti-tumor effect of IL-1β-induced-Th9 cells relied on IL-21 since the neutralization of IL-9 had a minor impact on anti-tumor properties under this circumstance." (PMID 32508847, 2020). "In addition, tumour standard uptake in the IL-21 injection group was increased by 17% compared to that in the control group indicating a higher rate of tumour glucose uptake." (PMID 32704112, 2020). "It was confusing that both pro-tumour and anti-tumour effect of IL-21 on CRC have been reported." (PMID 32760201, 2020). "In our experimental setting, we could demonstrate and increased tumor colony formation upon long term incubation with IL21 and IL26, and thus an increased ability to form more and larger vital tumor cell clusters." (PMID 31948053, 2020). "The tissue analysis implied that tumor cells acquire the receptor for IL-21." (PMID 31540511, 2019). "Importantly, although IL-21 is mainly secreted by T follicular helper cells, we found that tumor-infiltrating CD8+CXCR5+ T cells are able to induce B cells to differentiate into IgG-producing plasmablasts." (PMID 31663864, 2019). "Notably, TRAPs-elicited CD4+ T cells inhibited CD4+ and CD8+ effector T cell function in an IL-6- and IL-10-dependent manner and induced IL-10-producing regulatory B cells (Bregs) via IL-6, IL-10 and IL-21, thereby promoting tumor growth and metastasis." (PMID 31300052, 2019). "IL-21 anti-tumor effect is dependent on the activation of T, B and NK cells." (PMID 31307539, 2019). "Here, we have revealed a TRAPs-mediated regulatory mechanism of CD4+ T cells differentiation whereby HSP90α on the surface of TRAPs educate CD4+ T cells via a TLR2–autocrine IL-6 cascade to express IL-10 and IL-21 and engender immune suppression to promote tumor growth and metastasis." (PMID 31300052, 2019). "Furthermore, in breast cancer, IL-21 enhanced tumor cell proliferation and induced matrix metalloproteinases, the latter known to participate in tumor invasion." (PMID 31540511, 2019). "The role of IL-21 in tumor biology is controversially discussed." (PMID 31540511, 2019). "On a molecular level, the enhanced invasive capacity of the tumor cells could be attributed to Blimp-1, showing that Blimp-1 overexpression increased invasion, whereas its knockdown decreased IL-21-mediated tumor cell invasion." (PMID 31540511, 2019).
tumor (continued). "For example, the method developed by Cappuccio and co-workers for modeling IL-21 antitumor effects revealed that tumor load and IL-21 toxicity were minimized by optimizing the intervals between doses and the dosages, ensuring the highest efficacy/toxicity ratio." (PMID 30871264, 2019). "Here again Blimp-1 expression was significantly upregulated in IL-21 stimulated tumor cells." (PMID 31540511, 2019). "The TILs were then stimulated with the PanTT26 tumour cell line (autologous) three times to see whether repeated exposure of the IL-2/IL-15/IL-21-conditioned TILs to the tumour would lead to enrichment of tumour epitope-reactive T cells." (PMID 30377343, 2019). "The synergy between GM-CSF and IL-21 may be due in part to the ability of GM-CSF to stimulate dendritic cell maturation, which enhances the immunogenicity of tumor cells and effectively promotes TAA uptake." (PMID 31467912, 2019). "However, in the majority of tissues from PDAC patients, IL-21R was found on tumor cells, though to a varying degree, as were IL-21+ infiltrates." (PMID 31540511, 2019). "Moreover, several factors that induce tBregs are found in the tumor microenvironment, including TNF-α (secreted by tumor cells) and IL-21 (secreted by T cells)." (PMID 31248034, 2019). "For example, Th9 cells could activate the immune cells such as NK, hypertrophy immune cells, or promote the differentiation of Th17 cells by secreting IL-21 to lead to apoptosis of tumor cells." (PMID 31414895, 2019). "Consistent with an earlier study, we found that IL-21+ cells infiltrate the peritumoral and tumor tissues and may participate in antitumor immunity." (PMID 31663864, 2019). "IL-21/IL-21R signal pathway regulates both innate and adaptive immune systems, and is significant in inflammatory responses, the development of autoimmune diseases and inflammatory disorders, anti-tumor and antiviral response." (PMID 29316666, 2018). "The coexpression of BCL6 and IL21 in some of these PD-1+ cells indicates that Tfh differentiation occurs in the tumor microenvironment, presumably through the repeated and chronic exposure to quasi-self antigens (i.e., tumor antigens)." (PMID 30061879, 2018). "The addition of IFN-γ partially retrieved the IFN-γ-producing capacity of exhausted NK cells, whereas the addition of IL-21 completely restored the functions of NK cells isolated from H-2Kb and H-2Db KO tumours to levels comparable to those of NK cells isolated from WT tumours." (PMID 28585539, 2017). "Furthermore, the recovery of NK-cell function by IL-21 is critical for the anti-tumour effects of the vaccine against advanced tumours." (PMID 28585539, 2017). "In this regard, future studies should explore whether our vaccine could also restore the exhaustion of CD8+ T cells in tumour microenvironments through IL-21 produced by the activated NKT cells." (PMID 28585539, 2017). "A recent study has suggested that intratumoral delivery of IL21, in combination with anti-HER2 mAb therapy, enhances the therapeutic effects of trastuzumab, skewing tumor-associated macrophages away from a M2 phenotype to a tumor-inhibiting M1 phenotype." (PMID 29403144, 2017). "To determine whether IL-21 is capable of preventing tumour-mediated FOXP3 induction in naïve T cells, we repeated our naïve T cell stimulations in the presence of 50% cancer cell supernatants, alone or with recombinant human IL-21." (PMID 28239749, 2017). "FOXP3 expression was most potently induced by tumours secreting higher levels of total and active TGFβ1 and this induction could be potently counteracted with IL-21, restoring T cell proliferation." (PMID 28239749, 2017). "The administration of IL-21 and antibody-coated tumor cells leads to synergistic cytotoxic effects of NK cells toward tumor cells, which suggests that IL-21 may be an effective adjuvant for antibody treatment." (PMID 28824650, 2017).